MEG3 (maternally expressed 3)
Diseases named in the same sentence as MEG3 in open-access papers (continued):
Sharing a sentence is not in itself a finding about the gene and the disease.
multiple myeloma (11 papers, 2014 to 2024). "Upregulation of MEG3 promotes osteogenic differentiation of MSCs from multiple myeloma and pediatric aplastic anemia patients." (PMID 35054086, 2022). "Researchers have found that lncRNA MEG3 plays a critical role in the differentiation of osteoblasts in multiple myeloma, a hematological cancer that decreases bone mass by attenuating osteoblast proliferation and osteoblastogenesis." (PMID 30349507, 2018). "Overexpression of lncRNA MEG3 or administration of exogenous BMP4 remedied the osteogenic defects of MSCs derived from patients with multiple myeloma." (PMID 30349507, 2018). "Previous research demonstrated that MEG3 promoted osteogenic differentiation of MSCs from patients with multiple myeloma, and our recent study displayed a similar promotion of osteogenesis on hASCs with MEG3 overexpression." (PMID 29973283, 2018). "Additionally, MEG3 is downregulated in multiple myeloma where it acts as an endogenous competitive RNA with miR-181a, inhibiting tumor progression and possibly regulating HOXA11 by sponging miR-171a." (PMID 36869839, 2023). "Benetatos and colleagues studied the expression of MEG3 in multiple myeloma and found that, in approximately 60% of patients, the differentially methylated region (DMR) of the MEG3 promoter was hypermethylated." (PMID 38338876, 2024).
oral squamous cell carcinoma (11 papers, 2018 to 2025). "Among numerous lncRNAs, OIP5-AS1, MALAT1, UCA1, CCAT1, and MEG3 have been implicated in oral squamous cell carcinoma, and these lncRNAs were included in this study." (PMID 40568293, 2025). "LncRNA MEG3 inhibited the migration of oral squamous cell carcinoma cells and promoted apoptosis by regulating the JAK-STAT pathway." (PMID 36713226, 2022). "A recent study revealed that the expression of MEG3 was downregulated in oral squamous cell carcinoma and the overexpression of MEG3 negatively regulated the Wnt/β-catenin signaling pathway to inhibit the proliferation and metastasis of tumor cells." (PMID 36544907, 2022). "Subsequently, another study pointed out that rs11160608 of the MEG3 gene is related to the occurrence of oral squamous cell carcinoma in the Chinese population." (PMID 36544907, 2022). "One year later, another group from Chongqing Medical University suggested that MEG3 may regulate the proliferation and metastasis of oral squamous cell carcinoma cells by targeting miR-21." (PMID 36544907, 2022). "Furthermore, MEG3 was suggested to play tumour‐suppressive role in oral squamous cell carcinoma by impeding cell proliferation." (PMID 33332708, 2021). "We report that the lncRNA maternally expressed 3 (MEG3) was downregulated in oral squamous cell carcinoma (OSCC), and this was mediated by H3K27me3 modification of the MEG3 gene locus." (PMID 36468944, 2023).
psoriasis (11 papers, 2019 to 2026). An autoimmune condition characterized by red, well-delineated plaques with silvery scales that are usually on the extensor surfaces and scalp. "MEG3 and miR-147b, as non-coding RNAs, may show differential expression among psoriasis patient subgroups and could be associated with disease-related parameters, but their value as markers of disease severity or prognosis remains to be confirmed." (PMID 42156472, 2026). "MEG3 and miR-21 are suggested as potential biomarkers for psoriasis, while MEG3 also show distinct expression-patterns in therapy-resistant patient samples." (PMID 40981386, 2025). "LncRNAs have been revealed to participate in the pathogenesis of psoriasis, including MEG3, GAS5, and MIR31HG." (PMID 35586566, 2022). "For instance, MEG3/miR-21 axis contribute in the pathophysiology of psoriasis through modulation of caspase-8, cleaved caspase-8, cytc, and apaf-1." (PMID 32695942, 2020). "Then the relationship between lncRNA MEG3 and the expression of miR-21 in psoriasis was investigated." (PMID 31660855, 2019). "We aimed to unfold the influence of MEG3 and miR-21 on the proliferation and apoptosis of psoriasis epidermal cells." (PMID 31660855, 2019). "A cell model for in vitro studying the role of MEG3 in psoriasis pathophysiology was established using HaCaT and HHEKs." (PMID 31660855, 2019). "It was reported that differential expression of MEG3 was observed in psoriasis." (PMID 31660855, 2019). "In this study, we studied the influence of MEG3 on psoriasis keratinocytes in vitro, which may provide a new thought for the study of pathogenesis and treatment of psoriasis." (PMID 31660855, 2019). "MEG3/miR-21 axis may regulate the expression of caspase-8, and further influence the proliferation and apoptosis of psoriasis keratinocyte, Act-HaCaT and Act- HHEK." (PMID 31660855, 2019). "The finding in this study that MEG3 influenced the cell proliferation and apoptosis by regulating miR-21 could be a potential therapeutic target for the treatment of psoriasis." (PMID 31660855, 2019). "Therefore, there is a negative regulatory relationship between lncRNA MEG3 and miR-21, and lncRNA MEG3 should be a competitive endogenous substance of miR-21 in psoriasis." (PMID 31660855, 2019). "However, the influence of MEG3 on miR-21 during the proliferation and apoptosis of psoriasis epidermal cells remains unclear." (PMID 31660855, 2019). "Several lncRNAs are upregulated in psoriasis, such as MSX2P1, XIST, FABP5P3, KLDHC7B-DT, or SPRR2C, whereas MEG3, GAS5, PRINS or NEAT1 are downregulated in psoriasis." (PMID 38256115, 2024). "Other upregulated lncRNA in psoriasis are MIR31HG, MSX2P1, XIST, FABP5P3, KLDHC7B-DT, or SPRR2C; whereas, MEG3, GAS5, PRINS or NEAT1 are downregulated in psoriasis." (PMID 37628670, 2023). "While a number of lncRNAs such as MEG3, AL162231.4 and NONHSAT044111 have been down-regulated in the course of psoriasis, others including PRINS, MIR31HG, RP6‐65G23.1, MSX2P1, SLC6A14-1:1, NR_003062 have been up-regulated." (PMID 32695942, 2020).
retinoblastoma (11 papers, 2016 to 2025). A malignant tumor that originates in the nuclear layer of the retina. "The treatment of retinoblastoma cells with 5-Aza-CdR caused the demethylation of the MEG3 promoter, resulting in the upregulation of MEG3 and further inactivation of the Wnt/β-catenin pathway, leading to the inhibition of cell growth." (PMID 36851033, 2023). "Hypermethylation of MEG3 promoter was observed more frequently in retinoblastoma tissues and was highly associated with low MEG3 expression and poor survival of retinoblastoma patients." (PMID 29287592, 2017). "Our results indicated that hypermethylation of MEG3 promoter was significantly associated with retinoblastoma (R = 0.588)." (PMID 29287592, 2017). "In our previous study, we found that MEG3 was down-regulated in retinoblastoma and associated with IIRC stages, nodal or distant metastasis and prognosis." (PMID 29287592, 2017). "Moreover, Chi square test implied that hypermethylation of MEG3 promoter was not only related to but also a risk factor for retinoblastoma." (PMID 29287592, 2017). "In view of the fact that deletion, mutation or inactivation of RB Gene is one of the important causes of retinoblastoma, the regulation between MEG3 and RB protein maybe involved in the development of retinoblastoma." (PMID 29287592, 2017). "For MEG3 is a key factors for prognosis, we speculated that MEG3 methylation may be associated prognosis of retinoblastoma as well." (PMID 29287592, 2017). "Based on these, we proposed a hypothesis that methylation within the promoter region may be associated with loss of MEG3 expression in retinoblastoma as well." (PMID 29287592, 2017). "Moreover, the date also revealed that hypermethylation of MEG3 promoter was a risk factor for retinoblastoma (OR = 19)." (PMID 29287592, 2017). "However, only two lncRNAs, BANCR and MEG3, have been associated with retinoblastoma." (PMID 27043545, 2016). "For example, MEG3 is downregulated in both retinoblastoma and BC cells, and its overexpression suppresses proliferation while inactivating the PI3K/Akt/mTOR pathway, thereby reducing migration and enhancing apoptosis." (PMID 40350996, 2025). "The hypermethylation of the MEG3 promoter was also detected in retinoblastoma tissues and was correlated with the low expression of MEG3 and the poor survival of retinoblastoma patients." (PMID 36851033, 2023). "Reduced MEG3 expression by the hypermethylation of the MEG3 promoter increased β-catenin expression, promoting proliferation and inhibiting apoptosis in retinoblastoma cells." (PMID 36851033, 2023). "The inhibition of GSK-3β by its shRNA significantly reduced the role of MEG3 in regulating β-catenin and in promoting the invasion of retinoblastoma cells, suggesting that the GSK-3β protein is an important intermediator for the MEG3 functions." (PMID 36851033, 2023). "In our previous study, we revealed that MEG3 was a tumor suppressor gene in retinoblastoma and inhibited proliferation of retinoblastoma cells by regulating the activity of the Wnt/β-catenin pathway." (PMID 29287592, 2017). "The evaluation of the MEG3 methylation status can be a useful biomarker in determining the prognosis of patients with retinoblastoma." (PMID 29287592, 2017). "Treating the cells with a Wnt/β-catenin pathway activator reverses MEG3 over-expression induced anti-proliferation activity in retinoblastoma cell lines." (PMID 29069869, 2017). "To further examine the role of hypermethylation in down-regulation of MEG3 in retinoblastoma, we evaluated the effect of the 5-Aza-CdR on MEG3 expression." (PMID 29287592, 2017). "We first found that hypermethylation of MEG3 promoter occurred significantly more frequently in retinoblastoma tissues than in normal tissues." (PMID 29287592, 2017).
retinoblastoma (continued). "To identify mechanics of MEG3 lost, we first examined the methylation level of MEG3 promoter in 63 retinoblastoma tissues by MSP and evaluated the relationship between MEG3 methylation and prognosis of retinoblastoma patients." (PMID 29287592, 2017). "More important, our previous study has proved that down-regulation of MEG3 contributes to retinoblastoma progression by promoting the activity of Wnt/β-catenin pathway." (PMID 29287592, 2017). "We also provided evidence demonstrating that hypermethylation of MEG3 promoter depressed MEG3 expression, promoted proliferation, inhibited apoptosis and increased β-catenin expression of retinoblastoma cells in vitro." (PMID 29287592, 2017). "That means the methylation inhibitor of MEG3 promoter can be a novel therapeutic application for retinoblastoma." (PMID 29287592, 2017). "Decreased expression of MEG3 contributes to retinoblastoma progression and affects retinoblastoma cell growth by regulating the activity of Wnt/β-catenin pathway." (PMID 29069869, 2017). "In conclusion, our results revealed that aberrant promoter hypermethylation can lead to epigenetic inactivation of MEG3 and promotion of retinoblastoma cells growth." (PMID 29287592, 2017). "Studies have shown that MEG3 suppresses retinoblastoma progression by negatively regulating the Wnt/β-catenin pathway." (PMID 27043545, 2016). "It provides a new perspective in understanding the mechanism of MEG3 in retinoblastoma." (PMID 29287592, 2017). "In our previous study, we found that MEG3 could inhibit the activity of the Wnt/β-catenin pathway in retinoblastoma." (PMID 29287592, 2017). "In addition, one recent study showed that overexpression of MEG3 suppresses cell proliferation and promotes apoptosis by reducing the Wnt/β-catenin pathway activity in retinoblastoma cell lines." (PMID 29069869, 2017). "Collectively, these results indicate that aberrant MEG3 promoter hypermethylation maybe the major mechanism for MEG3 inactivation in retinoblastoma." (PMID 29287592, 2017). "To clarify the role of MEG3 methylation in regulation of proliferation and apoptosis in retinoblastoma cells, we used si-MEG3 to offset the effect of the 5-Aza-CdR on MEG3 re-expression and observed the change of biological characteristics of retinoblastoma cells." (PMID 29287592, 2017). "Then multivariate analysis confirmed that MEG3 methylation was retained as an independent prognostic indicator for patients with GC in addition to the presence of International Intraocular Retinoblastoma Classification (IIRC) stages, nodal or distant metastasis and optic nerve invasion." (PMID 29287592, 2017). "Then we revealed that 5-Aza-CdR maybe repress cell growth thought the pathway as follows: 5-Aza-CdR → demethylation of MEG3 promoter → up-regulation of MEG3 → inactivation of the Wnt/β-catenin pathway → growth inhibition of retinoblastoma cells." (PMID 29287592, 2017). "Furthermore, we testified the positive correlation between the hypermethylation of MEG3 promoter and the inactivation of MEG3 expression in retinoblastoma tissues." (PMID 29287592, 2017). "On the other hand, it demonstrated that MEG3 re-expression which due to demethylation could inhibit the growth of retinoblastoma cells." (PMID 29287592, 2017). "Interestingly, we found that the antitumor effects of 5-Aza-CdR were significantly repressed by si-MEG3 in retinoblastoma cells." (PMID 29287592, 2017). "What’s more, it also implied that the loss of MEG3 expression which was the result of hypermethylation in the MEG3 promoter could lead to malignant proliferation of retinoblastoma cells." (PMID 29287592, 2017). "Furthermore, we proved that MEG3 was a tumor suppressor by negatively regulating the activity of Wnt/β-catenin pathway in retinoblastoma." (PMID 29287592, 2017). "Here, we further explored the mechanism of MEG3 inactivation in retinoblastoma." (PMID 29287592, 2017).
retinoblastoma (continued). "In summary, it is recommended that patients with retinoblastoma and MEG3 hypermethylation should receive aggressive intervention following initial curative treatment to achieve more favorable outcomes and MEG3 methylation maybe a promising plasma biomarker for retinoblastoma." (PMID 29287592, 2017). "However, the exact mechanics of MEG3 lost in retinoblastoma remain elusive." (PMID 29287592, 2017). "A recent study indicated that MEG3 promoted β-catenin degradation via GSK-3β, which in turn inactivated the Wnt pathway and ultimately inhibited the invasion and metastasis of retinoblastoma cells." (PMID 36851033, 2023). "The results of microarray analysis showed that lncRNAs HOTAIR, CCAT1, DNM3OS, HIF1A‐AS1, MEG3 and 7SK expressions were up‐regulated, and lncRNAs PCAT1, MIR31HG, BCAR4, RRP1B and H19 were down‐regulated within retinoblastoma tissues." (PMID 30030888, 2018). "Our RT‐PCR results also verified that MEG3, HOTAIR, CCAT1 expressions within retinoblastoma tissues were far beyond those within para‐carcinoma tissues (P < 0.01)." (PMID 30030888, 2018). "In our previous study, we found that MEG3 expression, IIRC stages, and nodal or distant metastasis were independent prognostic factors for recurrence-free survival in retinoblastoma patients." (PMID 29287592, 2017). "However, the exact mechanics of MEG3 lost in retinoblastoma were still unknown." (PMID 29287592, 2017). "In the present study, MSP was used to evaluate the promoter methylation status of MEG3 in retinoblastoma tissues and corresponding non-tumor tissues." (PMID 29287592, 2017). "In the current study, the methylation status of MEG3 promoter in 63 retinoblastoma tissues and corresponding non-tumor tissues was detected by MSP." (PMID 29287592, 2017).
schizophrenia (11 papers, 2018 to 2026). A major psychotic disorder characterized by abnormalities in the perception or expression of reality. "Altered Meg3 levels have also been identified in blood of patients with Parkinson’s disease, clinically diagnosed psychosis, and schizophrenia, suggesting the possible use of Meg3 as a novel biomarker in human brain disorders." (PMID 35338311, 2022). "Decreased expression of MEG3 lncRNA has been reported in schizophrenia, Huntington’s disease and epilepsy." (PMID 35410190, 2022). "While Gomafu, PINT, GAS5, TCONS_l2_00021339, IFNG-AS1, FAS-AS1, PVT1, and TUG1 are among down-regulated lncRNAs in schizophrenia, MEG3, THRIL, HOXA-AS2, Linc-ROR, SPRY4-IT1, UCA1, and MALAT1 have been up-regulated in these patients." (PMID 34220567, 2021). "In genome-wide methylation arrays, MEG3 DMR methylation was associated with maternal smoking and in human adults, DLK1 dysregulation has been associated with schizophrenia." (PMID 30246009, 2018). "The expression of MEG3 lncRNA is decreased in schizophrenia, Huntington's disease, BD and epilepsy." (PMID 39482996, 2024). "Consequently, it is possible that MEG3 also affects the mentioned transmitters and participates in the evolution of schizophrenia." (PMID 31484957, 2019). "The effect of MEG3 gene variations on the susceptibility to DN could be another instance of genotype-gender interactions in human diseases, just as observations on variants of RELN gene with schizophrenia 46 and polymorphic alleles of ACE gene with hypertension." (PMID 40765563, 2025). "A former study has shown sex-specific dysregulation of HOXA-AS2, Linc-ROR, MEG3, SPRY4-IT1 and UCA1 lncRNAs in patients with schizophrenia." (PMID 35410190, 2022). "We have demonstrated up-regulation of HOXA-AS2, Linc-ROR, MEG3, SPRY4-IT1, and UCA1 in patients with schizophrenia compared with healthy subjects." (PMID 34220567, 2021). "We selected six lncRNAs namely HOXA-AS2, Linc-ROR, MEG3, SPRY4-IT1, UCA1 and MALAT1 to assess their expression in peripheral blood of patients with schizophrenia and healthy subjects." (PMID 31484957, 2019). "We also reported correlations between expressions of HOXA-AS2, MEG3 and UCA1 and age at disease onset in patients with schizophrenia." (PMID 31484957, 2019). "Expressions of HOXA-AS2, MEG3 and UCA1 were correlated with age at disease onset in patients with schizophrenia." (PMID 31484957, 2019). "Based on the acknowledged roles of lncRNAs in neurodevelopment, in the current study, we assessed expression of six lncRNAs namely HOXA-AS2, Linc-ROR, MALAT1, MEG3, SPRY4-IT1 and UCA1 in peripheral blood of 60 patients with schizophrenia and 60 healthy subjects." (PMID 31484957, 2019).
esophageal cancer (10 papers, 2020 to 2024). A primary or metastatic malignant neoplasm involving the esophagus. "Long non-coding RNA (lncRNA) maternally expressed gene 3 (MEG3) has been implicated in the progression of esophageal cancer (EC)." (PMID 34140005, 2021). "In addition, a previous study reported that MEG3 regulates T cell differentiation and contributes to immune escape in esophageal cancer." (PMID 35903713, 2022). "For instance, ectopic expression of MEG3 could accelerate the cell apoptosis in oesophageal cancer." (PMID 33332708, 2021).